CD4 (CD4 molecule)
Diseases named in the same sentence as CD4 in open-access papers (continued):
Sharing a sentence is not in itself a finding about the gene and the disease.
tumor (continued). "PD-1 and LAG-3 have been reported to be extensively co-expressed on CD4+, CD8+ T cells and particularly tumor-infiltrating T cells." (PMID 30603054, 2018). "Both anti-CD4 and anti-CD8 antibody-treated groups showed rapid tumor growth after cessation of X-ray treatment, but mouse IgG treatment did not have any effect on tumor growth." (PMID 29907739, 2018). "This study established down-regulating expression of membrane antigens that are indicative of the activation, differentiation, and maturation of tumor Jurkat T cells (CD3, CD4, CD8, and CD95) and reducing the secretion of IL-4 and TNFα." (PMID 29495627, 2018). "Tregs, abundant within the lamina propria in colon, suppress anti-tumor effector CD4+ and CD8+ T cells responses to maintain immune tolerance to tumor antigens and microbial antigens." (PMID 29997586, 2018). "Within the tumor microenvironment, human GITR is expressed on approximately 31 and 11% of CD4+ and CD8+ TILs, compared to nearly 100% of both cell types in murine tumor models." (PMID 30294332, 2018). "Immunohistochemistry revealed a marked increase in CD8+, CD4+, and CD20+ lymphocytes infiltrating the metastasis relative to the primary tumor." (PMID 29774030, 2018). "Tumor tissues from 80 GBC patients were analyzed by immunohistochemistry for the presence of CD3+, CD4+, CD8+, and Foxp3+ T cell populations, and the results were associated with clinical stage and patient survival." (PMID 29499656, 2018). "Flow analysis showed significantly higher tumor-infiltrating CD4+ T cells and CD8+ CTLs in the tumor microenvironment of FASNi- treated ID8 mice." (PMID 30619288, 2018). "Similar to cytokine production, cytotoxic activity was highest, when CD4+ and CD8+ PTM-transduced T cells were cocultured with tumor cells as compared to control conditions." (PMID 30214445, 2018). "With both methods, functionally active, antigen-specific CD4+ and CD8+ T-cells were detected at tumor sites 1 week following administration." (PMID 30386740, 2018). "Malignant T cells were primarily either double‐positive for CD4/CD8 or single‐positive for CD8 or single‐positive for CD4, with Lmo2 expression in the tumor T cells." (PMID 29880602, 2018). "The combined treatment resulted in increased CD4+ and CD8+ T-cells, and reduced myeloid-derived suppressor cells not only in the treated tumour, but also in the contralateral tumour site." (PMID 30261606, 2018). "Blockade of PD1/PD-L1 signaling pathway with αPD-L1 or SEP enhanced the frequency of CD4+ and CD8+ T cells in spleen and T cells infiltration into tumor." (PMID 29317734, 2018). "Effective T cell responses against tumors strongly depend on the differentiation pathways taken up by individual CD4+ and CD8+ T cells upon their interaction with tumor antigens." (PMID 30131808, 2018). "Murine tumor xenografts have shown that increasing levels of PD-1 and TIM-3 co-expression in CD4+ T-cells, CD8+ T-cells, and Tregs over time contribute to an exhausted or impaired T-cell phenotype." (PMID 29866197, 2018). "Our data demonstrate that PADRE increases the CD4+ Th1 subset population, and as a consequence, the immune response against TUBO tumour cells was greater than that of other groups and control." (PMID 28944998, 2018). "As support of this claim, we observed significant increases in both CD4+ and CD8+ T-cells within the same duration as the noted tumor enlargement." (PMID 29472563, 2018). "In conclusion, we performed TCR sequencing and IOCT analysis on anti-CD4 mAb treated tumor-bearing mice and demonstrated that anti-CD4 mAb treatment enhanced the expansion of a wide variety of CD8+ T cell clones in the dLN and their translocation to the tumor." (PMID 30733724, 2018). "Transduced CD4+ and CD8+ T cells in co-culture with tumor cells developed a predominant central memory phenotype over time." (PMID 30214445, 2018).
tumor (continued). "When addressing directly CD4+ T-cell functions, CD4+ T cells exhibited multifunctional cytokine responses to SVX peptides, with a predominant Th1 profile in vaccinated tumor-bearing animals." (PMID 30483475, 2018). "Nevertheless, ABX treatment had little effect on the apoptosis of tumor cells induced by diosgenin, and the group treated with ABX alone showed a weak CD4+/CD8+ T-cell infiltration." (PMID 30305604, 2018). "The activation status of CD4+, CD8+, and NK cells in the blood, lymph node, and/or tumor (7 days post-treatment) was evaluated by flow cytometry." (PMID 30400835, 2018). "We observed a correlation between the degree of expression of inflammatory transcripts in the tumor and the percentages of circulating central memory (CM) and effector (Eff) CD4+ and CD8+ T cells, expressed as independent CD4+ and CD8+ CM/Eff T cell ratios." (PMID 30123214, 2018). "It appears that IFN-γ and effector cells, that is, CD4+ and CD8+ lymphocytes, play an extremely important role in the recognition of tumor antigens." (PMID 29682586, 2018). "The specific depletion was achieved by administration of specific monoclonal antibodies against CD4 or CD8 antigens or with an isotype matched antibody that was used as a control, before tumor implantation." (PMID 30237863, 2018). "CD8+ cells, NK1.1+ cells and IFN-γ contributed to the anti-tumor effect of both ODN1826 and α-GalCer but MΦs reduced tumor growth only after administration of ODN1826 and this adjuvant stimulated also immunosuppressive CD4+ cells." (PMID 30469401, 2018). "Deficiency of miR-17-92 cluster in CD4+ T cells significantly impairs the Th1 cells response to B16 tumor cells, including a decrease in Th1 cells number and IFN-γ production and impairment in the ability of CD4+ T cells to help CD8+ T cells." (PMID 30443251, 2018). "T lymphocytes, notably related to tumor adaptive immune cells, are mainly divided into two hypotypes according to their function and phenotypes: T helper cells (Th: CD3+CD4+ T cells) and T cytotoxic cells (Tc:CD3+CD8+ T cells)." (PMID 30581487, 2018). "The presence of CD3+, CD4+, CD8+, and forkhead box protein P3-positive (FOXP3+) TILs in tumor tissues obtained from 93 patients during surgery was examined using immunohistochemistry." (PMID 30153850, 2018). "Further analysis showed elevated CD4+ and CD8+ T cell ratios in the tumor, as well as in the spleen after OxP or OxP+PD-L1 trap treatment in both models, and confirmed the effect of OxP in promoting anti-tumor responses." (PMID 29884866, 2018). "By contrast, a combination of day-10 CD4+ Th1 cells and CD8+ CTLs resulted in significantly higher tumour-free survival rate of 80% compared with that of day-10 CD8+ CTLs alone." (PMID 29114389, 2017). "Different subsets of mature T cells carry out the functions of cell-mediated immunity, including killing virally infected cells and tumor cells (CD8+ T cells) and providing help for and regulating components of the immune system (CD4+ T cells)." (PMID 28410575, 2017). "Our data suggest a dominant infiltrate of both CD4 and CD8 T cells within the perineural tumour mass and yet the tumour continues to grow." (PMID 28423034, 2017). "It is considered the most specific marker for CD4+/CD25+ and CD8+/CD25+ Treg lymphocytes, although its expression was also confirmed in tumor cells." (PMID 28343267, 2017). "In this study, we used the TCRmini mouse model for assessing changes in CD4+Teff and Treg TCR repertoires following experimental anti-tumor immunotherapy with the anti-GITR antibody." (PMID 28638937, 2017). "First, CD4+ T lymphocytes are required to eliminate (pre) malignant tumor cells, inhibit HCC initiation, and mediate tumor regression." (PMID 29262635, 2017). "CD4+ and CD8+ TILs promote an immunoreaction against these extraneous agents in a manner similar to tumor cells and enhance anti-tumor immunity." (PMID 28790445, 2017).
tumor (continued). "It is important to note that a substantial proportion of CD4+TIM-3+ TIL are Foxp3+, suggesting a role for TIM-3 in Treg within the tumor microenvironment (TME)." (PMID 28300768, 2017). "Although coordinated CD4+ and CD8+ responses are required for tumor control and rejection, the suboptimal performance of the current algorithms for prediction of class-II neoantigens limits their translational potential for personalized cancer medicine." (PMID 29234329, 2017). "Interestingly, the numbers of CD4+ T cells in the peritumoral tissue of livers collected in late stages of tumor progression were not increased when compared to those present in the early stages of liver metastasis when tumor cells are being retained in the liver." (PMID 29207960, 2017). "Our earlier preclinical work reported the ability of a subcutaneous viral based vaccination to trigger a detectable infiltration of the tumor environment by CD8+ and CD4+ lymphocytes." (PMID 28923084, 2017). "The results of a recently published study showed that CXCR3 was expressed on significantly fewer CD4+ and CD8+ T lymphocytes in tumor tissue compared to the unaffected tissue." (PMID 29020986, 2017). "Further, various studies have shown that tumor infiltrating lymphocytes (TILs) with higher tumor regression capability constituted of CD8+ and/or CD4+ T-cells specifically against neoantigens." (PMID 28304339, 2017). "IFN-γ production from both CD4+ and CD8+ T cells was observed after specific tumor-antigen stimulation." (PMID 28854279, 2017). "The number of CD4+, CD8+ and CD3+ T cells in the MC32A tumor microenvironment was lowest in CEA.Tg mice treated with mGITRL-FP alone." (PMID 29088720, 2017). "In contrast, an admixed formulation of E7 oligomers with CpG-loaded VLPs was sufficient to induce optimal CD4+ and CD8+ T cell responses that proved to be protective as a therapeutic vaccine when tested in an HPV tumor model." (PMID 28321220, 2017). "We have also determined the persistence of both CD4 Th1 and CD8 CTLs after clearance of both primary and secondary tumours." (PMID 29114389, 2017). "Further analysis of the role of T cells in host tumor resistance came from analysis of the progression of EMT6 and EMT6siCD200 tumors in WT mice treated with CD4 and CD8 depleting antibodies 6 days after tumor cell injection." (PMID 28234914, 2017). "However, HLA‐I‐redirected CD4+ T cells might also be capable of direct, efficient tumour lysis." (PMID 27324616, 2017). "In the tumor, AAV-IFNα reduced the percentage of T regulatory cells with a concomitant enhancement of the effect or CD4+ T lymphocytes." (PMID 28029653, 2017). "The strong influx of T cells together with the major induction of IFN-γ and cytotoxic molecules in Tlr−/− mice prompted us to test the relevance of CD4 and CD8 cells for tumour rejection in depletion experiments." (PMID 28300057, 2017). "Tumor antigen processing and presentation, including MHC I pathway and MHC II pathway, assist CD8 T cell to kill target cells and CD4 T cell to generate cytokine to activate other immune cells, respectively." (PMID 28432618, 2017). "Tumor rejection following vaccine and mGITRL-FP treatment was completely lost in mice depleted of CD8+ T cells alone and when combined with CD4+ T cell depletion." (PMID 29088720, 2017). "It is suggested that IL-10 can suppress the tumor development through the activation of natural killer, CD8+ and CD4+ T lymphocytes." (PMID 28846716, 2017). "Confirmation of the importance of such CD8+ cells came from monitoring tumor growth and characterization of the TILs and DLN cells in WT mice challenged with EMT6 and EMT6siCD200 tumors and treated with CD8 and CD4 depleting antibodies." (PMID 28234914, 2017). "IFN-γ production by type I NKT cell was found to be pivotal in inducing NK cell activation, proliferation of memory CD4+ and CD8+ T cell effector functions, and inhibiting angiogenesis, all contributing to effective immune response against tumor." (PMID 29018445, 2017).
tumor (continued). "These tumor-infiltrating CD4+ T cells expressed high CD25, which indicated the presence of Tregs, and this can be a result of conversion of CD4+CD25− cells into CD4+CD25+ cells in which TGF-β is involved." (PMID 28603527, 2017). "Weshowed that the microenvironment of SARC-L1 was highly infiltrated byCD3+ T cells which represents 76.8% ofCD45+ TILs.Among them the CD4 and CD8 T cell subsets represented 64.0% ± 3.5% and 8.12 % ± 0.9 % of tumor infiltrating lymphocytes(TILs) respectively." (PMID 28430664, 2017). "Antigen-presenting cells (APCs), such as tumor-associated macrophages (TAMs) and dendritic cells (DC), take up TAAs from tumor cells debris and present their peptides in the context of MHC to TAA-specific CD8+ and CD4+T-lymphocytes." (PMID 28220118, 2017). "When immunized CD4+ cells and immunized CD8+ cells were transfused into scid mice, the survival rate was 50% at 4 weeks after tumor inoculation, but the tumors persisted intraperitoneally." (PMID 28864944, 2017). "Taking advantage of immunocompetent Tgfbr1/Pten‐knockout HNSCC models, we observed restoration of effector T cells by targeting CD4+TIM3+ cells and CD8+TIM3+ cells and decreasing MDSCs in tumor microenvironment and peripheral environment." (PMID 28102051, 2017). "Specific subpopulations of T cells in sham or tumor-bearing hemispheres were detected by staining with antibodies against CD8, CD4 and intracellular FOXP3; MDSCs were detected by staining with anti-CD11b and anti-Gr1 antibodies." (PMID 29242629, 2017). "CD4+CD25+FoxP3+ Treg cells are capable of suppressing Th1/CTL responses and represent a major mechanism of tumor escape in several cancers." (PMID 28229253, 2017). "Orally administered YM-2A enhanced antitumor immune response by increasing INF-γ-expressing CD4+ and CD8+ cells in the spleen and INF-γ-expressing CD8+ cells in tumor-draining lymph nodes." (PMID 28278221, 2017). "In contrast to LS174T and SW948, tumor cells lysis of H508 tumor cells was low for both CD25− and CD25+ CD4+ T cells, respectively." (PMID 28850063, 2017). "Importantly, this increased Treg proliferation was not responsible for the expansion of the antigen-experienced memory CD4+ T cells (manuscript in preparation), as might be predicted by a study using another tumor model where Tregs primarily contributed to the CD137+CD44+CD4+ memory compartment." (PMID 27966460, 2017). "We also analyzed the relation between PD-L1 expression and three key indicators of the intra-tumoral immune response, CD8, CD4, and CD68 tumor infiltrating leucocytes (TIL)." (PMID 28881675, 2017). "[CD8+] / [CD4+/CD25+/CD127low] ratio was similarly decreased in tumor (4.4 ± 4.5) and mucosa (4.0 ± 2.7), being statistically significant between tumor samples and PBMC HNSCC (4.4 ± 4.5 vs. 7.8 ± 6.4; p < 0.05)." (PMID 28574843, 2017). "In a colon-26 tumor model, oral administration of YM-2A induced IFN-γ expression by CD4+ T cells in the spleen, and CD8+ T cells in the spleen and TDLNs." (PMID 28278221, 2017). "When CD4+ T cells in EMT6 and EMT6siCD200 tumor bearing WT hosts were depleted, a reduction in EMT6 tumor growth was observed with a trend to similarly decreased growth of EMT6siCD200 tumors." (PMID 28234914, 2017). "Subsequent experimental data included CD4+ and CD8+ T cells ratio, Th1 cytokine contents in spleen, and anti-tumor efficacy and provided evidence at this point." (PMID 29196724, 2017). "Staining of tumor tissue of patient 7 showed low expression of PD‐L1 and low counts of CD4‐ and CD8‐positive cells with high CD8/CD4 ratio." (PMID 28639409, 2017). "In contrast to the observation made in regard to CD4+ T cell count in peritumoral areas, CD8+ T cells count did diminished in regions surrounding the tumor foci within livers inoculated with β2-C26 cells." (PMID 29207960, 2017).
tumor (continued). "Meanwhile, the TIM3 expression on CD4+ T cells and CD8+ T cells was down‐regulated by the blockade of TIM3, especially in tumor and LN, as the ratio of TIM3+ cells in CD4+ or CD8+ T cells was found to be decreased." (PMID 28102051, 2017). "The frequencies of CD4+ and CD8+ T cells in spleens of tumor mice and their activation status were significantly increased in HPV-CGN-DC group, but the frequencies of natural regulatory T cells and CD11b+Gr-1+ cells were significantly decreased." (PMID 28404904, 2017). "The percentages of CD4+ and CD8+ cells were increased in the tumor of the mice injected with MDSCs transfected with RNCR3 siRNA as compared to control, indicating the reduced suppressive ability in RNCR3 knockdown MDSCs." (PMID 29340089, 2017). "We determined that the combination immunotherapy facilitated tumor infiltration of effector CD8+ and CD4+ T cells (expressing IFN-γ, ICOS, granzyme B, and perforin), while reducing the prevalence of PD-L1+ cells and exhausted PD-1+CD8+ TIL in the TME." (PMID 28555136, 2017). "CD4+ T cells are responsible for promoting the functions of CD8+ cells and favor the elimination of tumor cells." (PMID 28848246, 2017). "This study provides significant information on TIL subsets, such as CD3+, CD4+, CD8+, and Foxp3+, and indicates that they can be used as prognostic biomarkers for HCC or as targeted molecules for anti-tumor treatment." (PMID 28790445, 2017). "Treatment with anti-CD4 markedly increased the number of CD8+ T cells in the DLN of both EMT6 and EMT6siCD200 tumor bearing mice." (PMID 28234914, 2017). "Foxp3+, CD4+, and CD8+ T cells in tumoural and stromal areas were evaluated by immunohistochemistry." (PMID 28322245, 2017). "We found that anti-IL-17A Ab injection inhibits PDL1 expression in tumor cells, macrophages, and MDSCs, decreased the number of Treg cells in TILs, and increased the number of IFN-γ-producing CD4+ and CD8+ T cells in TILs in ER-negative tumor-bearing mice." (PMID 27935862, 2017). "Irradiated lymphopenic mice were reconstituted with ex vivo—expanded CD4+ T cells and inoculated with MCA205 tumor cells." (PMID 28854279, 2017). "Upon treatment, CD4+ T cells are recruited in the tumors, enhance and maintain CD8+ T cell activation, and induce MHC-II expression on tumor cells through the release of IFNγ, leading to their recognition and death." (PMID 29403144, 2017). "On the other hand, recent evidence demonstrated that the number of CD4+CD25+FOXP3+ regulatory T cells (Treg), which mediate immunosuppression and play an important role in tumour immune evasion, also increases with age." (PMID 28253320, 2017). "An immunohistochemistry analysis of tumor-infiltrating lymphocytes (TILs) showed that CD8+ CTLs and, to a lesser extent, CD4+ T lymphocytes and Treg cells were present in UM inflammatory infiltrates." (PMID 28229253, 2017). "Hepa1-6 tumor bearing mice after three rounds of treatment with HMGN1, R848 and anti-CTLA4 showed significantly increased infiltration of CD3+, CD4+, and CD8+ T cells in tumor tissues." (PMID 28881713, 2017). "TIM3 blockade increased the effector T cells, CD4+ and CD8+ T cells in tumor microenvironment and peripheral environment, especially in tumor and LN." (PMID 28102051, 2017). "CD4 helper cells were found to be critical to this effect, suggesting that MYC oncogenicity occurs not only through tumor-intrinsic mechanisms but also through host-dependent immune mechanisms." (PMID 29163537, 2017). "The present study scored stromal, intratumoral, and global TIL (as a percentage of the defined area), TLS as well as CD3+, CD4+, CD8+, and CD20+ TIL as a percentage of the defined stromal, tumor, and global areas." (PMID 29163490, 2017). "TEM among CD4+ and CD8+ T-cells in tumor tissues was more frequent than TCM and Tnaïve T-cells in tumor tissues." (PMID 29213216, 2017).